NDRG2 (NDRG family member 2)
Diseases named in the same sentence as NDRG2 in open-access papers (continued):
Sharing a sentence is not in itself a finding about the gene and the disease.
malaria (1 paper, 2022). Malaria is a serious and sometimes fatal disease caused by a parasite that commonly infects a certain type of mosquito which feeds on humans. "Genes in cluster 4, underrepresented in symptomatic malaria and upregulated by asymptomatic infection, included several genes encoding protein products mediating negative regulation of immune processes, such as the anti‐proliferative molecules BTG1 and NDRG2, as well as the checkpoint receptor CD83." (PMID 35475529, 2022).
mesothelioma (1 paper, 2025). A usually malignant and aggressive neoplasm of the mesothelium which is often associated with exposure to asbestos. "Additionally, we discovered that the genes SOAT1, TACC3, and NDRG2 are linked to the prognosis of mesothelioma patients." (PMID 40223054, 2025). "Currently, there are no research reports on the roles of SOAT1, TACC3, and NDRG2 in mesothelioma." (PMID 40223054, 2025).
metastatic melanoma (1 paper, 2012). A melanoma that has spread from its primary site to another anatomic site. "Therefore, the expression pattern of human NDRG2, VDR, NSD1, CTCF and SRC genes in several human metastatic melanoma cell lines in comparison to primary melanocytes were analyzed at mRNA level by RT-qPCR methodology." (PMID 22984562, 2012).
multiple sclerosis (1 paper, 2019). A progressive autoimmune disorder affecting the central nervous system resulting in demyelination. "Multiple sclerosis is a demyelinating disease, disrupting the communication between parts of the nervous system.NDRG2 was investigated in the context of neuroinflammation, using an NDRG2KO mouse in an experimental model of multiple sclerosis (experimental autoimmune encephalomyelitis (EAE))." (PMID 31485792, 2019).
Myocardial fibrosis (1 paper, 2013). "Elucidation of the biological function of NDRG2 in HF may provide a promising strategy for the treatment of myocardial fibrosis." (PMID 24303125, 2013).
ovarian carcinoma (1 paper, 2020). A malignant neoplasm originating from the surface ovarian epithelium. "Consistent with its expression pattern, NDRG2 acts as a tumor suppressor within ovarian cancer cell lines." (PMID 32345304, 2020). "In summary, we attempt to provide a solid experimental basis for understanding the cellular functions of NDRG2 on ovarian cancer cells." (PMID 32345304, 2020). "Herein, the mRNA and protein expression of NDRG2 showed to be dramatically downregulated within the ovarian cancer tissues than that in the normal controls." (PMID 32345304, 2020). "NDRG2 overexpression dramatically suppressed the proliferation whereas enhanced the apoptosis of ovarian cancer cells, similarly to its effects on other cancers." (PMID 32345304, 2020). "The NDRG2 inhibition capacity towards holding the growth and tumorigenesis of ovarian cancer in vivo was evaluated on xenograft nude mice model." (PMID 32345304, 2020). "The NDRG2 inhibition capacity towards holding the growth and tumorigenesis of ovarian cancer was determined in vivo." (PMID 32345304, 2020). "More importantly, NDRG2 overexpression significantly enhanced the suppressive roles of cisplatin (DDP) in ovarian cancer cell viability." (PMID 32345304, 2020). "Herein, we revealed that NDRG2 mRNA expression and protein levels were downregulated within both ovarian cancer tissues and cell lines." (PMID 32345304, 2020). "To further confirm how NDRG2 affected ovarian cancer, we first verified NDRG2 expression within the tissues and cells of ovarian cancer." (PMID 32345304, 2020). "We revealed that NDRG2 mRNA expression and protein levels were downregulated within both ovarian cancer tissues and cell lines." (PMID 32345304, 2020). "More importantly, NDRG2 overexpression significantly enhanced the suppressive roles of DDP in ovarian cancer cell viability." (PMID 32345304, 2020). "DDP treatment dramatically inhibited cell viability; NDRG2 overexpression enhanced the suppressive role of DDP in the viability of ovarian cancer cells, whereas NDRG2 silence exerted an opposing effect." (PMID 32345304, 2020). "Herein, NDRG2 mRNA and protein expression showed to be monitored within ovarian cancer tissues and cells." (PMID 32345304, 2020). "To further investigate the specific effects of NDRG2 on ovarian cancer cells, we conducted NDRG2 overexpression and NDRG2 silence in SKOV3, OVCAR-3, and CAOV3 cells by transfection with vector (negative control), NDRG2 OE, si-NC (negative control), or si-NDRG3." (PMID 32345304, 2020). "Nevertheless, little is known about the specific role of NDRG2 within ovarian cancer." (PMID 32345304, 2020). "After confirming the tumor-suppressive effect of NDRG2 on ovarian cancer cells, we further investigated whether NDRG2 could sensitize ovarian cancer cells to DDP treatment." (PMID 32345304, 2020). "NDRG2 administration presents a potent adjuvant treatment for ovarian cancer therapy." (PMID 32345304, 2020). "The overexpression of NDRG2 dramatically inhibited the cell viability and colony formation and tumor growth, whereas promoted the cell apoptosis, cell cycle arrest in G1 phase within ovarian cancer cells." (PMID 32345304, 2020). "Next, the effects of NDRG2 overexpression and silence on ovarian cancer cells were evaluated." (PMID 32345304, 2020). "NDRG2 overexpression attenuated the growth and tumorigenesis of ovarian cancer in vivo." (PMID 32345304, 2020). "Next, NDRG2 overexpression and silence were conducted in three cell lines of ovarian cancer; the specific effects of NDRG2 upon the viability, colony formation ability, apoptosis, cell cycle, and the sensitivity to cisplatin (DDP) treatment of ovarian cancer cells were evaluated." (PMID 32345304, 2020). "Here, we attempted to investigate the specific roles of NDRG2 in ovarian cancer." (PMID 32345304, 2020). "On the contrary, NDRG2 silence exerted opposing effects on ovarian cancer cells." (PMID 32345304, 2020).
ovarian carcinoma (continued). "In summary, NDRG2 could improve the cellular effects of DDP on ovarian cancer cells." (PMID 32345304, 2020). "Therefore, NDRG2 overexpression attenuated the growth and tumorigenesis of ovarian cancer in vivo." (PMID 32345304, 2020). "In the present study, NDRG2 overexpression within ovarian cancer cell lines significantly enhanced the suppressive effects of DDP upon the viability of ovarian cancer cells, whereas NDRG2 silence exerted an opposing effect." (PMID 32345304, 2020).
papillary thyroid carcinoma (1 paper, 2010). "At present, researchers' attention has been concentrating on NDRG2 (N-Myc downstream-regulated gene 2) as a new gene candidate in the development and progression of papillary thyroid carcinoma (PTC)." (PMID 20804549, 2010). "Up to date, only one study concerning the NDRG2 gene expression in papillary thyroid carcinoma has been published in the medical literature." (PMID 20804549, 2010).
parasitemia (1 paper, 2022). "NR1D1, NDRG2, and PLD4 showed significant negative correlations with parasitemia, suggesting that downregulation of transcription could be driven by high parasite burden and/or the concomitant inflammation associated with symptomatic infection." (PMID 35475529, 2022).
Parkinson disease (1 paper, 2025). A progressive degenerative disorder of the central nervous system characterized by loss of dopamine producing neurons in the substantia nigra and the presence of Lewy bodies in the substantia nigra and locus coeruleus. "NDRG2 is highly expressed in astrocytes of the central nervous system and was also demonstrated to be expressed in the brains of humans with Parkinson’s disease and corticobasal degeneration." (PMID 40378957, 2025).
retinal degeneration (1 paper, 2018). Degeneration of the retina. "The most important finding of the current study is to unravel NDRG2 as the molecular hallmark of photoreceptor-specific cell viability, which was confirmed not only in vitro but also in vivo in retinal degeneration and treatment." (PMID 30245855, 2018). "Our findings revealed a previously unrecognized role of NDRG2 in mediating photoreceptor cell homeostasis and established for the first time the molecular hallmark of photoreceptor-specific cell death as NDRG2 suppression, shedding light on improved understanding and therapy of retinal degeneration." (PMID 30245855, 2018).
rheumatoid arthritis (1 paper, 2021). A chronic, systemic autoimmune disorder characterized by inflammation in the synovial membranes and articular surfaces. "The latest evidence shows that rheumatoid arthritis tissues express comparatively low levels of NDRG2 and that silencing NDRG2 promotes the proliferation and inflammation of fibroblast-like synoviocytes." (PMID 34551684, 2021).
small cell lung carcinoma (1 paper, 2025). Small cell lung cancer (SCLC) is a highly aggressive malignant neoplasm, accounting for 10-15% of lung cancer cases, characterized byrapid growth, and early metastasis. "Additionally, NDRG2 can negatively regulate the progression of small cell lung cancer through the PTEN-AKT-mTOR signaling pathway." (PMID 40223054, 2025).
Sotos syndrome (1 paper, 2022). Sotos syndrome is a rare multisystemic genetic disorder characterized by a typical facial appearance, overgrowth of the body in early life with macrocephaly, and mild to severe intellectual disability. "In conclusion, we propose that NSD1 may participate in Sotos syndrome’s mechanism of action by regulating the function of lncRNA, inducing the down-expression of GSC, NDRG2 and SORBS1 and the up-expression of SFN and ZNF883." (PMID 35888078, 2022).
thyroid (1 paper, 2008). "Future studies are needed to address whether the down-regulation of NDRG2 is a cause or a consequence of the progression from a normal thyroid to a carcinoma." (PMID 18940011, 2008). "The expression profiles of Ndrg2 in the microarray of thyroid tissues suggested an important role for Ndrg2 in thyroid carcinogenesis." (PMID 18940011, 2008). "We thus wanted to analyze the expression level of Ndrg2 protein in adjacent normal and neoplastic thyroid tissues from human patients to confirm the results." (PMID 18940011, 2008). "Our data indicates that NDRG2 may participate in thyroid carcinogenesis." (PMID 18940011, 2008).
Thyroid adenoma (1 paper, 2008). The presence of a adenoma of the thyroid gland. "In this study, we investigated the expression profile of human NDRG2 in thyroid adenomas and carcinomas, by examining tissues from individuals with thyroid adenomas (n = 40) and carcinomas (n = 35), along with corresponding normal tissues." (PMID 18940011, 2008). "We also observed reduced expression of Ndrg2 protein in a few samples of thyroid adenomas." (PMID 18940011, 2008). "A slight decrease in NDRG2 was detected in the thyroid adenoma tissues." (PMID 18940011, 2008). "We also noted that Ndrg2 expression decreased slightly in thyroid adenomas, though the difference was not statistically significant (p > 0.1)." (PMID 18940011, 2008). "Although the slight decrease of NDRG2 expression in thyroid adenomas was not significant, it suggests that NDRG2 might be involved in mediating the progression from thyroid adenoma to carcinoma." (PMID 18940011, 2008).
ulcerative colitis (1 paper, 2021). An inflammatory bowel disease involving the mucosal surface of the large intestine and rectum. "In patients with ulcerative colitis, reduced NDRG2 expression is positively correlated with severe inflammation." (PMID 34551684, 2021).
uveal melanoma (1 paper, 2017). A melanoma derived from melanocytes of the uveal tract. "Promoter hypermethylation was extensively observed in the ITGA7, NDRG2 and PITX2 genes (85% methylated samples) in uveal melanoma." (PMID 28924151, 2017).
tumor (122 papers, 2007 to 2026). "Numerous studies have documented that NDRG2 promoter hypermethylation leads to its downregulation, which is associated with higher tumor grade, increased aggressiveness, and worse patient prognosis." (PMID 41596413, 2026). "Previous studies have linked the suppression of NDRG2 expression in tumor cells to hypermethylation, which is primarily controlled by DNMTs." (PMID 41596413, 2026). "A prior study demonstrated that hypermethylation of the NDRG2 promoter region is significantly associated with increased tumor aggressiveness and resistance to standard therapies." (PMID 41596413, 2026). "Inhibition of IκBα phosphorylation diminishes M1 marker expression, emphasizing NF-κB’s pivotal role in the tumor-suppressive functions of NDRG2-deficient macrophages." (PMID 40764998, 2025). "Specifically, a significant association was found between low NDRG2 expression and tumor grade, as well as disease stage." (PMID 38668066, 2024). "N-MYC downstream-regulated gene 2 (NDRG2) is a candidate tumor-suppressor, while MMPs can cause cancer metastasis via ECM protein degradation and triggering cell invasion." (PMID 37450923, 2024). "Among this family, NDRG2 is known as a tumor suppressor gene that is associated with tumor incidence, metastasis, and progression." (PMID 37958443, 2023). "Studies have shown that NDRG2 plays an important role in regulating the polarization and inflammatory response in tumor-associated macrophages (TAMs)." (PMID 36572898, 2022). "As a tumor suppressor or stress response gene, NDRG2 is involved in the anti-metastasis and antiproliferation of tumor cells, and is implicated in responses to stress responses, which involve hormones, ions, body fluid metabolism, hypoxia, and lipotoxicity." (PMID 34685629, 2021). "NDRG2 is suppressed in various aggressive tumor positions, whereas NDRG2 expression is associated with patient prognosis, such as an improved survival rate." (PMID 34685629, 2021). "In this review, we summarize the tumor suppressor mechanism of NDRG2 and provide information on the function of NDRG2 concerning the susceptibility of cells to apoptosis." (PMID 34685629, 2021). "NDRG2 regulates the pathological processes associated with tumor aggressiveness, such as proliferation and invasion/epithelial–mesenchymal transition (EMT) in various tumors." (PMID 34685629, 2021). "A better understanding of the molecular mechanisms underlying the function of NDRG2 in tumorigenesis and tumor progression helps us elucidate prognostic results." (PMID 33031336, 2020). "Herein, we demonstrate that metastatic tumor obtained a mesenchymal phenotype, which is obtained by the loss of tumor suppressor NDRG2 triggered metabolic switch to glutamine metabolism." (PMID 33162818, 2020). "Mechanistic study indicates that the increased Akt activity and c-Myc stability play key roles in the induction of ASCT2-dependent glutaminolysis and the tumor aggressive phenotype, responding to the loss of NDRG2 expression in metastatic MC3 cells." (PMID 33162818, 2020). "Here the NDRG2 gene is located, a tumor suppressor gene that has been associated with c-MYC and the TGF-β pathway in colorectal carcinogenesis, and its epigenetic silencing promotes tumor proliferation and invasiveness." (PMID 30813366, 2019). "Functionally, it has been described that NDRG2 has an antiproliferative effect, so loss of NDRG2 would be beneficial for tumor growth." (PMID 31485792, 2019). "It is therefore still likely that loss of NDRG2 expression is related to tumor aggressiveness, although it is difficult to draw any conclusions regarding the correlation with protein expression." (PMID 31485792, 2019). "Now, a new study published in this issue of Cell Death and Disease has made the surprising discovery that NDRG2 in tumor-associated macrophages (TAMs) programs them for M2 polarization and thereby aids metastases outgrowth of NDRG2 wild-type (WT) cancer cells." (PMID 29463798, 2018).
tumor (continued). "Taken together, the loss of NDRG2 induced macrophages toward a pro-inflammatory and tumor-suppressor phenotype." (PMID 29445150, 2018). "A previous study reported that NDRG2 can inhibit IL-10 expression, which plays an important role in tumor-associated immune response by modulating SOCS3 and STAT332." (PMID 29445150, 2018). "To confirm that the loss of Ndrg2 in BMDMs inhibited tumor growth, we established a mixed model of tumor cells and macrophages." (PMID 29445150, 2018). "NDRG2 is known to be a tumor-suppressive protein associated with the clinicopathological features of various tumors." (PMID 29348517, 2018). "Although loss of NDRG2 expression as a clinical marker has mostly been associated with poor outcome in patients suggesting a tumor-suppressor role, a recent study has observed the opposite correlation for patients with basal-like breast cancer." (PMID 29463798, 2018). "NDRG2 regulates tumor-associated genes and is regulated by multiple conditions, treatments, and protein/RNA entities, including hyperthermia, trichostatin A and 5-aza-2′-deoxycytidine, which are promising potential cancer therapeutics." (PMID 26506239, 2016). "The NDRG2 gene is involved in cell differentiation and tumor suppression; partial or complete loss ofNDRG2 expression is observed in several aggressive tumors." (PMID 27007654, 2016). "The down-regulation of NDRG2 expression is associated with higher tumor recurrence and lower survival rate." (PMID 26506239, 2016). "A putative tumor suppressor gene implicated in cancer development and progression is NDRG2, a member of the N-myc downstream-regulated gene family." (PMID 27400234, 2016). "The associations between NDRG2 expression and tumor incidence as well as clinical and pathological tumor behavior have been clarified." (PMID 26506239, 2016). "Recent studies indicated decreased NDRG2 expression due to promoter DNA-hypermethylation, underlining a possible tumor suppressive role of NDRG2 in breast carcinogenesis." (PMID 27400234, 2016). "Ndrg2 methylation was strongly associated with late stage tumors, but the association of Ndrg2 methylation level with patient survival is independent on the tumor stage." (PMID 25823664, 2015). "To identify the underlying target molecules regulated by NDRG2 in tumor aerobic glycolysis, we analyzed the expression of glucose transporters and glycolytic pathway-related enzymes in NDRG2-overexpressing and NDRG2-knockdown Caco-2, HT-29 and HCT116 cells." (PMID 26317652, 2015). "To identify the underlying target molecules regulated by NDRG2 in tumor glutaminolysis, we analyzed the expression of glutamine transporters and glutaminolytic pathway-related enzymes in NDRG2-overexpressing and NDRG2- knockdown HCT116 cells." (PMID 26317652, 2015). "Immunoblotting of protein extracted from the same set of patients' samples confirmed the association of NDRG2 down-regulation with features of tumor metastasis, suggesting NDRG2 involvement in HCC aggressiveness." (PMID 25261367, 2014). "NDRG2 has been implicated as a tumor suppressor in a number of malignancies, but the molecular mechanisms still have to be explored in more detail." (PMID 23056173, 2012). "HCC with low NDRG2 expression was strongly associated with CD24 overexpression in tumor tissues (P = 0.04)." (PMID 21676268, 2011). "The to-date's research has indicated that an increased expression of Myc oncogene is associated with decreased NDRG2 gene expression in many neoplasms." (PMID 20804549, 2010). "This trend indicates either that the loss of NDRG2 promotes tumor progression or that NDRG2 is inactivated by factor(s) present at advanced tumor stages." (PMID 17935612, 2007). "N-myc downstream regulated gene 2 (NDRG2) acts as a tumor suppressor in HCC, yet its underlying mechanisms remain unclear." (PMID 41991725, 2026). "Loss of NDRG2 expression is associated with tumor metastasis by inducing EMT via NF-κB activation." (PMID 36012631, 2022).